BCAT1 (branched chain amino acid transaminase 1)
Diseases named in the same sentence as BCAT1 in open-access papers (continued):
Sharing a sentence is not in itself a finding about the gene and the disease.
pancreatic cancer (7 papers, 2020 to 2025). "In conclusion, the present study demonstrated that BCAT1 contributes to chemoresistance in pancreatic cancer cells." (PMID 39926331, 2025). "TFEB, a key regulator of autophagy, reprograms the metabolism of BCAAs by transcriptionally regulating the BCAT1 and thus influences pancreatic cancer progression." (PMID 38938061, 2024). "Moreover, the proliferation and invasion status induced by ACSS2 can be partly reversed by BCAT1 in pancreatic cancer cells." (PMID 40908872, 2025). "Moreover, with the support of molecular docking, we demonstrate that bufalin directly binds to BCAT1 and increases the sensitivity of pancreatic cancer cells to gemcitabine and 5-fluorouracil." (PMID 39926331, 2025). "Besides, we explored the relationship between TFEB/BCAT1 expression and the clinicopathological features of pancreatic cancer." (PMID 38938061, 2024). "Further assessment of cell viability in MIA PaCa-2 and PANC-1 cells treated with bufalin, the identified inhibitor of BCAT1, revealed IC50 values of 0.26 ± 0.046 μM and 0.32 ± 0.086 μM, respectively, indicating an effective outcome in pancreatic cancer." (PMID 39926331, 2025). "This further validated the transcriptional regulation of BCAT1 by TFEB, which also implied that pancreatic cancer cells acquire metabolic shifts favouring their survival through the TFEB‐BCAT1‐BCAAs pathway." (PMID 38938061, 2024). "In this study, we demonstrated that TFEB in pancreatic cancer cells (PCCs) regulates the BCAA metabolism pathway, which is essential for cell proliferation and metastasis, by regulating BCAT1, a key enzyme in BCAA metabolism." (PMID 38938061, 2024). "IHC staining and combined prognostic analysis of clinical samples from patients with pancreatic cancer revealed that patients with double positivity (high expression) for TFEB and BCAT1 tended to have a poorer prognosis." (PMID 38938061, 2024). "A 3-gene signature consisting of LY6D, BCAT1, and ITGB6 based on 538 DEGs between both subtypes serves as a stable prognostic marker in patients with pancreatic cancer across multiple cohorts." (PMID 34976806, 2021). "The expressions of LY6D, BCAT1, and ITGB6 in 120 cases of pancreatic cancer and 30 cases of para-carcinoma were detected by immunohistochemistry." (PMID 34976806, 2021). "Our immunohistochemical results showed that LY6D, BCAT1, and ITGB6 were all overexpressed in pancreatic cancer, which was consistent with the previous results." (PMID 34976806, 2021). "Finally, the molecular mechanisms by which LY6D, BCAT1, and ITGB6 drive the malignant progression of pancreatic cancer require further verification." (PMID 34976806, 2021). "The LY6D, BCAT1, and ITGB6 genes were upregulated in pancreatic cancer samples." (PMID 34976806, 2021).
lung adenocarcinoma (5 papers, 2022 to 2024). A carcinoma that arises from the lung and is characterized by the presence of malignant glandular epithelial cells. "Patients with high BCAT1 protein levels in lung adenocarcinoma tissues were associated with a poor prognosis." (PMID 38993559, 2024). "BCAT1 expression was significantly higher in lung adenocarcinoma brain metastases than in primary lung adenocarcinoma (P = 0.021)." (PMID 38993559, 2024). "We then compared BCAT1 expression in 72 lung adenocarcinoma samples and 118 lung adenocarcinoma brain metastases." (PMID 38993559, 2024). "We observed that the glycolysis/gluconeogenesis pathway was enriched as the top differential pathway in the BCAT1-high lung adenocarcinoma samples relative to the BCAT1-low tumors." (PMID 39143065, 2024). "Therefore, after inhibition of BCAT1 expression in lung adenocarcinoma cells, we first examined the levels of BCAAs and α-KG in cells via LC-MS/MS." (PMID 38993559, 2024). "BCAT1 was highly expressed in lung adenocarcinoma brain metastases." (PMID 38993559, 2024).
non-alcoholic fatty liver disease (5 papers, 2018 to 2024). "Expression and methylation of the BCAT1 gene are associated with human nonalcoholic fatty liver disease." (PMID 38028625, 2023).
Obesity (5 papers, 2013 to 2023). Accumulation of substantial excess body fat. "The DMPs annotated to genes CPT1A, NLRC5 and BCAT1, which were associated with three out of four anthropometric indices studied, combined attributed to 7.6% of the variance on obesity." (PMID 28947923, 2017). "In addition, BCAT1 methylation was found to be associated with obesity, elevated plasma BCAAs for obesity states, BCAT1 as a candidate gene associated with obesity, and obesity associated with type 2 diabetes." (PMID 38028625, 2023). "Nucleotide-binding oligomerization domain-like receptor family caspase recruitment domain containing 5 (NLRC5) cg07839457 and branched chain amino acid transaminase 1 (BCAT1) cg20399616 were significantly associated with BMI, obesity and WC." (PMID 36397166, 2022). "DMPs cg07839457 and cg20399616, annotated to genes NLRC5 and BCAT1, respectively, were associated with BMI, WC and obesity but not with abdominal obesity." (PMID 28947923, 2017). "DMP cg07839457 (NLRC5) and cg20399616 (BCAT1) were significantly associated with BMI, obesity and with WC and had not been reported by previous EWAS on adiposity." (PMID 28947923, 2017). "DMP cg20399616 annotated to gene BCAT1 was hypo-methylated in relation to BMI, WC and obesity." (PMID 28947923, 2017). "Notably, we found three DMPs or loci (CPT1A, NLRC5 and BCAT1) that showed epigenome-wide significance with both obesity and abdominal obesity." (PMID 28947923, 2017). "The odds for the obesity were 0.85, 1.04 and 0.94 for the DMPs annotated to genes CPT1A, NLRC5 and BCAT1, respectively." (PMID 28947923, 2017). "Eight genes (BCAT1, BMP2 K, CSRNP2, MYNN, NCKAP5L, SAP30BP, SLC35B4, and SP1) were isolated as candidates for obesity." (PMID 24455749, 2013). "In contrast, only three DMPs—cg00574958, cg07839457 and cg20399616—, annotated to genes CPT1A, NLRC5 and BCAT1, respectively, were significantly differentially methylated in those with obesity compared with those without." (PMID 28947923, 2017).
pancreatic ductal adenocarcinoma (5 papers, 2018 to 2024). An infiltrating adenocarcinoma that arises from the epithelial cells of the pancreas. "SMAD5 is translocated into the nucleus and interacts with the BCAT1 promoter to stimulate BCAT1 expression in cancer-associated fibroblasts from pancreatic ductal adenocarcinoma (PDAC) tumors when the transforming growth factor is activated." (PMID 36358687, 2022). "The study has shown that the metabolism of Branched-chain amino acids (BCAA) is potentially linked with development of pancreatic ductal adenocarcinoma, and BCAT1, an enzyme involved in the degradation of branched-chain amino acids, is responsible for initiating the catabolism of such amino acids." (PMID 34976806, 2021). "For instance, BCAT1 inhibition in pancreatic ductal adenocarcinoma (PDAC) didn’t inhibit tumor growth, with lower BCAT1 expression in tumors and higher BCAA levels in plasma." (PMID 38309289, 2024). "It has been reported that pancreatic ductal adenocarcinoma cells reprogram fibroblasts to upregulate the expression of BCAT1, to meet the cancer cells’ demand for branched-chain α-ketoacid (BCKAs) under BCAA deprivation." (PMID 34976806, 2021). "Likewise, suppression of BCAT1 in pancreatic ductal adenocarcinoma (PDAC) did not lead to a reduction in tumor growth, and patients with PDAC expressed low levels of tumor BCAT1 and displayed increased plasma BCAAs levels [12▪]." (PMID 29211698, 2018).
prostate carcinoma (5 papers, 2021 to 2025). A carcinoma that arises from epithelial cells of the prostate gland. "An increase in BCAT1 expression has been reported in several cancers and is closely associated with malignant progression, but its expression in prostate cancer is unknown." (PMID 38369471, 2024).
lymphoma (4 papers, 2013 to 2025). A malignant (clonal) proliferation of B- lymphocytes or T- lymphocytes which involves the lymph nodes, bone marrow and/or extranodal sites. "A BCAT1 antagonist diminished outgrowth of BCR/TLR9-driven lymphomas in vivo, including a patient-derived xenograft (PDX)." (PMID 40924473, 2025). "A BCAT1 antagonist diminished outgrowth of BCR/TLR9-driven lymphomas in vivo, including a patient derived xenograft." (PMID 38854072, 2024). "Median expression levels were invariably higher for AURKB, BCAT1, BIRC5, BUB1B, PBK and RACGAP1 and lower for FOSB, MAP3K1 and RIN3 by qPCR in lymphoma versus normal B cell samples in both species." (PMID 24130802, 2013). "BCAT1 inhibition blunted BCR/TLR9, but not CD40L/IL4-triggered B-cell proliferation, IL10 expression and BCR/TLR pathway-driven lymphoma xenograft outgrowth." (PMID 38854072, 2024).
adenoma (3 papers, 2014 to 2021). A neoplasm arising from the epithelium. "Although methylated markers such as RASSF1A, SDC2, BCAT1, IKZF1, ALX4, SDC2 and WIF-1, among others, have demonstrated some usefulness for the detection of established cancers, the goal of detecting precancerous adenomas has not been achieved yet." (PMID 32605302, 2020).
Alzheimer disease (3 papers, 2022 to 2025). A progressive, neurodegenerative disease characterized by loss of function and death of nerve cells in several areas of the brain leading to loss of cognitive function such as memory and language. "For example, the pathogenic classification of BCAT1 variant rs371256913 is supported by emerging evidence linking BCAT1 dysfunction to Alzheimer’s disease through autophagy regulation." (PMID 41256702, 2025). "Given that autophagy dysfunction is increasingly recognized as central to Alzheimer’s disease pathogenesis, the BCAT1 pathway represents a convergence point between metabolic dysfunction and protein aggregation, which supports the pathogenic classification of BCAT1 variants in Alzheimer’s disease." (PMID 41256702, 2025).
Burkitt lymphoma (3 papers, 2013 to 2025). A rare form of malignant mature B-cell non-Hodgkin lymphoma. "We stably expressed TMEM192 in Rael Burkitt lymphoma B cells, in which BCAT1 and LAMP1 colocalization was increased by αIgM + CpG stimulation." (PMID 40924473, 2025). "We stably expressed TMEM192 in Rael Burkitt lymphoma Rael B-cells, in which BCAT1 and LAMP1 co-localization was increased by aIgM+CpG stimulation." (PMID 38854072, 2024).
esophageal squamous cell carcinoma (3 papers, 2019 to 2022). Esophageal squamous cell carcinoma (ESCC) is a type of esophageal carcinoma (EC) that can affect any part of the esophagus, but is usually located in the upper or middle third. "Esophageal squamous cell carcinoma (ESCC) was associated with BCAT1." (PMID 36119495, 2022).
liver cancer (3 papers, 2021 to 2025). An epithelial or non-epithelial malignant neoplasm that arises from the liver. "Again, low levels of BCAT1 is a good prognostic marker for HCC and oral supplementation with branched chain amino acids has been shown to reduce the risk of liver cancer in cirrhotic patients." (PMID 33594203, 2021). "For example, the decreased methylation level of the BCAT1 promoter in HCC tissues leads to increased BCAT1 expression, over activating the AKT signaling pathway and promoting epithelial-to-mesenchymal transition (EMT), thereby facilitating the occurrence and metastasis of liver cancer cells." (PMID 40028341, 2025).
osteosarcoma (3 papers, 2020 to 2023). A usually aggressive malignant bone-forming mesenchymal neoplasm, predominantly affecting adolescents and young adults. "Among them, MAN2B1, P4HA2, ANPEP, BCAT1, CTSS, and DAPK1 were significantly correlated with the prognosis of patients with osteosarcoma." (PMID 37457661, 2023).
Parkinson disease (3 papers, 2022 to 2024). A progressive degenerative disorder of the central nervous system characterized by loss of dopamine producing neurons in the substantia nigra and the presence of Lewy bodies in the substantia nigra and locus coeruleus. "A recent screen for curling identified the bcat-1 gene to be associated with a Parkinson's-like phenotype and knockdown of the gene transcript showed altered mitochondrial function." (PMID 35707205, 2022).
triple-negative breast carcinoma (3 papers, 2020). An invasive breast carcinoma which is negative for expression of estrogen receptor (ER), progesterone receptor (PR), and human epidermal growth factor receptor 2 (HER2). "Silencing or knockdown of BCAT1 has been associated with reduced growth of triple negative breast cancer." (PMID 34766125, 2020). "Previous studies have shown that branched-chain amino acid transferase 1 (BCAT1) is associated with tumour progression in triple-negative breast cancer (TNBC)." (PMID 32571264, 2020).
acute myocardial infarction (2 papers, 2022 to 2023). Necrosis of the myocardium, as a result of interruption of the blood supply to the area. "Activation of BCAT1 and inhibition of oxoeicosanoid receptor can reduce acute myocardial infarction." (PMID 38028625, 2023). "Cytosolic branched-chain aminotransferase (BCAT1) has been identified as a genomic biomarker for cardiotoxicity studies; it is also down-regulated in acute myocardial infarction and experimentally heart-specific upregulation of BCAT1 is protective against ischemic myocardial injury." (PMID 35614104, 2022). "Activation of BCAT1 can also reduce acute myocardial infarction; overexpression of BCAT in the heart can improve myocardial ischemic injury; and targeted treatment of BCAT is a promising strategy for acute myocardial infarction for clinical treatment." (PMID 38028625, 2023).
Arthritis (2 papers, 2017 to 2020). Inflammation of a joint. "Furthermore, Bcat1 inhibition is also associated with reduced macrophage migration in vitro and decreased tissue infiltration in arthritis and glomerulonephritis." (PMID 28699638, 2017). "Here the authors show that BCAA metabolism affects the broken Krebs cycle, reprogramming macrophages to be less proinflammatory, and show that BCAT1 inhibitor ERG240 can treat arthritis in mice and glomerulonephritis in rats." (PMID 28699638, 2017).
autoimmune disease (2 papers, 2017 to 2024). A disorder resulting from loss of function or tissue destruction of an organ or multiple organs, arising from humoral or cellular immune responses of the individual to their own tissue constituents. "In summary, we show that blocking Bcat1 results in therapeutic outcome in two independent models of autoimmune diseases with end-organ damage (joints and glomeruli)." (PMID 28699638, 2017). "The druggability of Bcat1 in autoimmune disease was shown with the utilization of ERG240, a novel Bcat1 inhibitor." (PMID 28699638, 2017).
Autoimmunity (2 papers, 2024 to 2025). The occurrence of an immune reaction against the organism's own cells or tissues. "BCAT1 may therefore constitute an intriguing metabolic vulnerability, including in MCD DLBCL and in certain autoimmunity states, including systemic lupus erythematosus, where BCR/TLR7 drives pathology." (PMID 38854072, 2024).
B cell lymphoma (2 papers, 2024 to 2025). "BCAT1 inhibition significantly impaired growth of BCR/TLR9-pathway dependent MDC DLBCL xenografts in vivo, identifying BCAT1 as a promising novel B-cell lymphoma therapeutic target." (PMID 38854072, 2024). "BCAT1 inhibition significantly impaired growth of BCR/TLR9 pathway–dependent MDC DLBCL xenografts in vivo, identifying BCAT1 as a promising B cell lymphoma therapeutic target." (PMID 40924473, 2025).
breast invasive carcinoma (2 papers, 2022 to 2024). "BCAT1 levels have been positively associated with tumor progression and worse prognosis in invasive breast cancer and TNBC." (PMID 38971778, 2024).
cervical cancer (2 papers, 2021 to 2024). A primary or metastatic malignant neoplasm involving the cervix. "The expression levels of BCAT1 were detected by qRT-PCR and Western blotting in the cervical cancer cell line (Hela) and HCC cell lines (HepG2 and Huh-7) treated with cisplatin." (PMID 33568627, 2021). "It is worth noting that BCAT1/Leu/mTOR/Autophagy is a concise mechanism for the cisplatin sensitivity of cervical cancer and HCC cells." (PMID 33568627, 2021). "In this study, we further revealed that BCAT1-regulated cisplatin sensitivity in cervical cancer (Hela) and HCC (HepG2 and Huh-7) cells in vitro and in vivo." (PMID 33568627, 2021). "Furthermore, we demonstrated a new mechanism that the cisplatin-induced up-regulation of BCAT1 decreased the cisplatin sensitivity in cervical cancer and HCC cells by regulating mTOR-mediated autophagy via BCAA metabolism." (PMID 33568627, 2021). "In our study, the CQ and 3-MA treatment significantly enhanced the sensitivity of the cervical cancer and HCC cells to cisplatin in vivo and in vitro and partially relieved the BCAT1-induced resistance to cisplatin." (PMID 33568627, 2021). "The overexpression of BCAT1 increases LC3B-II expression and suppresses p62 expression in Hela and Huh-7 cells, whereas the knockdown of BCAT1 decreases LC3B-II expression and increases p62 expression in HepG2 cells, indicating that BCAT1 induces autophagy in cervical cancer and HCC cells." (PMID 33568627, 2021).
colon cancer (2 papers, 2015 to 2020). "Longitudinal follow-up studies are required to understand whether the low false-positive rate in healthy cases reflects chance events (i.e. methylation of BCAT1 DNA especially) of no consequence, or an early indication of colorectal neoplasia and/or other extra-colonic cancers." (PMID 26445409, 2015).
esophageal cancer (2 papers, 2022 to 2023). A primary or metastatic malignant neoplasm involving the esophagus. "Additionally, DNMT1 indirectly regulates BCAT1 by methylating miR-124-3, which directly targets BCAT1 to affect the proliferation and migration of esophageal cancer cells." (PMID 37781524, 2023).
experimental autoimmune encephalomyelitis (2 papers, 2024 to 2025). An autoimmune demyelinating disease of the central nervous system that is produced experimentally in animals by the injection of homogenized brain or spinal cord in Freund's adjuvant. "To examine the systemic in vivo effect of BCAT1 inhibition, we adopted an experimental autoimmune encephalomyelitis (EAE) model widely utilized for studying the pathogenic responses of autoreactive Th17 cells." (PMID 39085353, 2024). "In an experimental autoimmune encephalomyelitis (EAE) model, blocking BCAT1-mediated leucine catabolism using BCAT1 inhibitors or LβhL treatment alleviated the severity of EAE by reducing HIF1α expression and IL-17 production in spinal cord mononuclear cells." (PMID 40438606, 2025). "In an in vivo experimental autoimmune encephalomyelitis (EAE) model, blockade of BCAT1-mediated leucine catabolism, either through a BCAT1 inhibitor or LβhL treatment, mitigated EAE severity by decreasing HIF1α expression and IL-17 production in spinal cord mononuclear cells." (PMID 39085353, 2024).
germ cell tumor (2 papers, 2019 to 2022). A benign or malignant, gonadal or extragonadal neoplasm that originates from germ cells. "The increased expression of BCAT1 in NTERA-2 cells compared to TCam-2 cells seems also of interest in distinguishing germ cell tumor subtypes." (PMID 31565104, 2019).
head and neck squamous cell carcinoma (2 papers, 2022). A squamous cell carcinoma that arises from any of the following anatomic sites: lip and oral cavity, nasal cavity, paranasal sinuses, pharynx, larynx, and salivary glands. "Further analyses on head and neck squamous cell carcinoma certified upregulated BCAT1 expression at both mRNA and protein levels in this disease based on in‐house tissue microarrays and multicenter datasets." (PMID 34984849, 2022). "Furthermore, we analyzed BCAT1 expression in head and neck squamous cell carcinoma (HNSCC) based on larger samples from in‐house tissue microarrays and public datasets." (PMID 34984849, 2022). "In addition, studies have found that high levels of BCAT1 were related to the proliferation and migration of head and neck squamous cell carcinoma (HNSC) cells." (PMID 36119495, 2022).